CRP (C-reactive protein)
Diseases named in the same sentence as CRP in open-access papers (continued):
Sharing a sentence is not in itself a finding about the gene and the disease.
colorectal cancer (continued). "In recent years, C-reactive protein (CRP) has been widely studied as an early predictor of septic complications, including AL, after elective colorectal cancer (CRC) surgery." (PMID 35055369, 2022). "Circulating CRP level after diagnosis is also part of the modified Glasgow Prognostic score, which is clinically used as inflammation-based prognostic parameter in colorectal cancer patients." (PMID 35739525, 2022). "For colorectal cancer, there was evidence for mediating effect through fasting insulin, while the point estimates for indirect effects through leptin and CRP, and estradiol were essentially null." (PMID 35048536, 2022). "Recently, some scholars have proposed that the CRP/ALB ratio (CAR) can predict postoperative complications in a timely manner in colorectal cancer, and its predictive value is better than that of CRP alone." (PMID 33727917, 2021). "More explicitly, recent colorectal cancer research has indicated a strong relationship between suboptimal patient physiological stage, increased comorbidity, and elevated CRP." (PMID 32865623, 2021). "LCR, a combination of lymphocyte count and CRP, was correlated with oncological outcomes including recurrence and survival in patients with colorectal cancer, intrahepatic cholangiocarcinoma, and gastric cancer." (PMID 34778081, 2021). "In one retrospective study of 84 colorectal cancer patients, serum CRP and calprotectin levels were assessed for 5 days following surgery." (PMID 34070593, 2021). "In one retrospective study of 1187 colorectal cancer patients, CRP levels and WBCC were assessed for the first 5 days following surgery." (PMID 34070593, 2021). "This study suspected that Grade 3 or higher SSI induced poor prognosis in patients with systemic inflammatory responses, such as a high neutrophil–lymphocyte count ratio and high CRP, which has been shown in patients with advanced colorectal cancer." (PMID 34406563, 2021). "For the specific group of older patients with colorectal cancer, one of the most common cancers diagnosed, the preoperative plasma level of CRP was also an independent prognostic factor for overall survival up to three years after surgery." (PMID 33920422, 2021). "It has been confirmed that high level of CRP was correlated with unfavorable survival in esophageal carcinoma, colorectal carcinoma, as well as multiple myeloma." (PMID 34221991, 2021). "In 2013, Lin's study reported that cases with colorectal cancer (CRC) had a poor prognosis when CRP levels were above 5 mg/L." (PMID 33201589, 2020). "With the establishment of a post-operative CRP threshold, potential factors giving rise to an elevated post-operative CRP are being increasingly identified in operable colorectal cancer." (PMID 32348308, 2020). "Previous studies have shown that C-reactive protein (CRP) can predict the occurrence of complications and even the severity of postoperative complications in colorectal cancer." (PMID 32172320, 2020). "The prognostic impact of the combination of the modified Glasgow prognostic score (mGPS) and C-reactive protein/albumin ratio (CAR) in colorectal cancer (CRC) is unclear." (PMID 33105743, 2020). "Systemic inflammatory response (SIR), defined as elevated circulating C-reactive protein (CRP), prior to colorectal cancer (CRC) surgery has been established as an independent risk factor for impaired survival." (PMID 32316975, 2020). "It has been reported with increased levels of CRP was relevant to poor prognosis in colorectal cancer, hepatocellular carcinoma, and esophageal carcinoma." (PMID 30847301, 2019). "Third, some studies have found the prognostic value of the ratio CRP/Albumin in tumours, such as oesophageal squamous cell cancer, ovarian cancer, and colorectal cancer." (PMID 31781301, 2019). "Recently, further researches have demonstrated a correlation of high CRP level with a poor prognosis in colorectal cancer, osteosarcoma, hepatocellular carcinoma, and other cancers, as well as in NPC patients." (PMID 30847301, 2019).
colorectal cancer (continued). "CRP levels at 72 h postoperatively were found to be predictive of major complications in patients that underwent open and minimally invasive surgery for colorectal cancer." (PMID 29282574, 2018). "The CRP level was significantly higher in the colorectal cancer patients than that in the control subjects (p < 0.001)." (PMID 29874787, 2018). "MMP-9 and CRP serum levels have a significant predictive value in the assessment stage II to IV colorectal cancer which points to persisting inflammation-related process and its importance in the colorectal tumor genesis." (PMID 30154846, 2018). "The aim of this study to evaluate mutual relation between IL-6, CRP and MMP-9 serum levels in patients with CRC and their association with staging and clinical-pathological features of colorectal cancer." (PMID 30154846, 2018). "Italian authors also demonstrated an increase in CRP serum levels in the patients with colorectal cancer, particularly in the second and third stages of the disease, comparable to the tendency we found." (PMID 30154846, 2018). "CRP is a marker of systemic inflammation, with a convincing prognostic influence in colorectal cancer." (PMID 29929486, 2018). "The aim of this study was to evaluate interleukin-6 (IL-6), C-reactive protein (CRP), matrix metalloproteinase-9 (MMP-9), serum levels in patients with colorectal cancer (CRC), and their association with the stage of CRC." (PMID 30154846, 2018). "In a study of 695 colorectal cancer cases and 1846 controls, we derived a reduced rank regression dietary pattern using 32 food groups as predictors and the plasma C-reactive protein (CRP) concentration as the response." (PMID 29874787, 2018). "The magnitude of the postoperative systemic inflammatory response (SIR), as evidenced by C-reactive protein (CRP), is associated with both short- and long-term outcomes following surgery for colorectal cancer." (PMID 28251379, 2017). "The aim of this retrospective study was to evaluate the significance of the C-reactive protein to albumin (CRP/ALB) ratio in colorectal cancer patients who received palliative chemotherapy." (PMID 27812440, 2016). "Several inflammatory biomarkers, such as C-reactive protein, have been reported in the colorectal cancers process." (PMID 27153562, 2016). "The literature evidence regarding the association of circulating concentrations of inflammatory biomarkers, other than CRP, IL-6, and TNF-α, and the risk of colorectal cancer is very sparse." (PMID 26321888, 2015). "All three patients had abnormally high CRP levels (range 53 mg/L–178 mg/L) and one patient who also suffered from colorectal cancer died during the initial hospital admission." (PMID 25374597, 2014). "Several studies have reported an association between elevated serum CRP levels and malignant diseases other than RCC, including colorectal cancer, lung cancer and urothelial cancer." (PMID 25013512, 2014). "Table I shows the correlation between clinicopathological characteristics and CRP status in patients with stage I–III colorectal cancer." (PMID 23833661, 2013). "Multivariate analysis identified high CRP levels as an indicator or predictor of both nodal and distant metastasis in T3 colorectal cancer." (PMID 24148787, 2013). "Preoperative C-reactive protein (CRP) is known to be a useful tool in predicting postoperative outcomes in patients with colorectal cancer." (PMID 23833661, 2013). "In conclusion, preoperative CRP provides an independent prognostic value for colorectal cancer in stages I–III and is superior to the currently used number of lymph nodes harvested or pN stage." (PMID 23833661, 2013). "In the present study, the prognostic potency of CRP was validated for patients with colorectal cancer (CRC) in order to guide patient management and define high-risk populations for follow-up or for therapeutic purposes." (PMID 24255664, 2013).
colorectal cancer (continued). "This confirmed the stronger prognostic value of the LNR or preoperative CRP status in patients with stage III colorectal cancer." (PMID 23833661, 2013). "Findings from studies in patients with colorectal cancer have indicated that those with elevated serum CRP concentrations had poorer prognoses than those whose CRP level did not increase." (PMID 20465852, 2010). "Mean and median levels of VEGF and CRP in the colorectal cancer group were significantly higher than in the normal control group; 620 vs. 334 pg/mL and 541 vs. 312 pg/mL (p < 0.001); 1.12 vs. 0.43 mg/dL and 0.25 vs. 0.07 mg/dL (p = 0.001)." (PMID 20465852, 2010). "The aim of this study was to determine preoperative serum levels of VEGF, IL-6, and CRP in colorectal carcinoma, and to correlate them with disease status and prognosis." (PMID 20465852, 2010). "Others suggested that the pre-operative serum elevation of both IL-6 and CRP are good prognostic predictors in colorectal cancer patients." (PMID 19341447, 2009). "In many cancers such as esophageal cancer, gastric cancer and colorectal cancer, serum CRP was known as a prognostic indicator." (PMID 19707535, 2009). "As serum CRP levels have previously been shown to be associated with acute inflammation, the present lack of positive associations between higher serum CRP levels and increased risk of colorectal cancer may be due in part to the population-based method used in the present follow-up study." (PMID 16127232, 2005). "The OR of the highest serum CRP levels was 1.18 (95% CI: 0.68-2.06) for colorectal cancer and 1.42 (95% CI: 0.73-2.74) for colon cancer, compared to subjects with lowest serum levels." (PMID 16127232, 2005). "In summary, the results of the present study show that, in patients undergoing curative resection for colorectal cancer, low tumour CD4+ T-lymphocyte infiltration is associated with elevated C-reactive protein concentrations." (PMID 15700032, 2005). "The OR of the highest serum CRP levels for colorectal cancer was 1.07 (95% CI: 0.64-1.78), compared to the subjects with the lowest serum levels." (PMID 16127232, 2005). "The OR of the highest serum CRP levels for incident cases of colorectal cancer was 0.97 (95% CI: 0.51-1.83) after adjusting for the confounding factors, compared to the subjects with the lowest serum levels." (PMID 16127232, 2005). "We used t-test to analyze mean differences in CRP levels between colorectal cancer cases and controls." (PMID 16127232, 2005). "The value of combining Dukes' stage and C-reactive protein to form a cumulative prognostic score was assessed in 147 patients undergoing potentially curative resection for colorectal cancer." (PMID 15150596, 2004). "This suggests that postoperative CRP levels can serve as an independent predictor of POD in colorectal cancer patients, aiding clinicians in the early identification and intervention for high-risk POD patients among elderly colorectal cancer patients." (PMID 39958614, 2025). "This study evaluated esketamine's effects on serum biomarkers of oxidative stress (glutathione, catalase, malondialdehyde, superoxide dismutase), inflammatory mediators (TNF-a, CRP IL-6), and T lymphocyte subsets in patients undergoing laparoscopic colorectal cancer resection." (PMID 40951888, 2025). "Therefore, a higher CRP/albumin ratio is a biomarker of inflammation and is considered a prognostic factor for overall survival in both gynecological and colorectal cancers." (PMID 40523478, 2025). "A pronounced CRP response has been shown to correlate with a diminished overall- and colorectal-specific survival, as well as recurrence-free survival in patients undergoing colorectal cancer surgery." (PMID 40383853, 2025). "Shibutani Shibutani M M Prognostic significance of the preoperative serum C-reactive protein level in patients with stage IV colorectal cancer Prognostic significance of the preoperative serum C-reactive protein level in patients with stage IV colorectal cancer Surg." (PMID 40664764, 2025).
colorectal cancer (continued). "To assess the effect of periodontal treatment on colorectal cancer, we measured the CRP levels in the blood during cancer therapy on the day of the initial examination by the oncological surgeon, two days following surgery, and at the first follow-up appointment." (PMID 40272186, 2025). "CRP measurement on POD 3 is useful for predicting ALs in colorectal cancer surgery patients." (PMID 39735081, 2024). "In this study, we investigated the potential of preoperative inflammatory serum markers, including Interleukin-6 (IL-6), C-reactive protein (CRP) and Interleukin-8 (IL-8), as biomarkers for long-termn survival in patients with curatively resectable colorectal cancer (CRC) and liver metastases." (PMID 38233759, 2024). "Numerous predicted ratios and scores based on inflammatory associated variables, such as NLR, PLR, CRP/ALB, and modified Glasgow prognostic score (mGPS) have been applied to predict the prognosis of colorectal cancer, gastric cancer, lung cancer and other cancer." (PMID 37089594, 2023). "A small RCT showed that colorectal cancer patients who received preoperative probiotics had significantly lower levels of plasma endotoxin, D-lactic acid, interleukin-6, and C-reactive protein and higher levels of IgG and IgA immunoglobulins after colectomy compared to the control group." (PMID 36986061, 2023). "Another study showed that the lymphocyte/CRP ratio might represent a new prognostic marker in patients with colorectal carcinoma." (PMID 37750127, 2023). "Although observational studies have reported associations between serum C-reactive protein (CRP) concentration and risks of lung, breast, and colorectal cancer, inconsistent or absent evidences were showed for other cancers." (PMID 36117174, 2022). "Moreover, platelet count was proved that positively correlated with serum levels of C-reactive protein (CRP) in colorectal cancer (CRC)." (PMID 34983483, 2022). "Inflammatory cytokines such as IL−6, CRP and sCD40L have been shown to reflect the progression of colorectal cancer and predict tumor relapse, but most of them are postulated as indirect surrogate prognosis factors due to their correlation with already established WHO pathological grading criteria." (PMID 35204454, 2022). "Inconsistently positive results for breast and colorectal cancer could be a result of increased CRP levels due to an already present but undiscovered malignancy." (PMID 34926085, 2021). "Additional sensitivity analyses, presented for models for colorectal cancer, involved evaluating the influence of participants with extreme CRP concentrations or lymphocyte counts or with regular aspirin use, but excluding such participants did not affect the HR estimates." (PMID 34036468, 2021). "It was recently reported that the lymphocyte–CRP ratio (LCR), a novel prognostic score based on the preoperative lymphocyte count and CRP, has emerged as an independent indicator of poor prognosis in various cancers, including colorectal cancer, gastric cancer, and hepatocellular carcinoma." (PMID 34778081, 2021). "Associations between circulating C-reactive protein and serum IgE and colorectal cancer risk were not identified." (PMID 31668584, 2020). "The increase of preoperative CRP reflects the ongoing inflammatory reaction and is related to the decrease of lymphocytes, which leads to the impairment of cell-mediated immune function in patients with colorectal cancer." (PMID 33299880, 2020). "CRP, a member of the pentraxin family, was found as an important prognostic marker in patients with several malignancies, including lung, urological, pancreatic, hepatocellular, and colorectal cancers." (PMID 33364190, 2020). "It is worth noting that a meta-analysis did not identify any association between CRP 1846C>T polymorphism and the risk of colorectal cancer." (PMID 31142628, 2019).
colorectal cancer (continued). "Previously, several studies have reported that laboratory parameters reflecting inflammation, such as the NLR and serum CRP level, may be related to the prognosis of cancer, for example, GC, colorectal cancer, and lung cancer." (PMID 31238937, 2019). "Significant positive correlation between IL-6 and CRP serum levels was confirmed in the patients with CRC strongly suggesting that CRP as a general marker of inflammation should be combined with the other inflammatory molecules in patients with colorectal cancer." (PMID 30154846, 2018). "Colorectal cancer patients had higher CRP levels than did controls (P < 0.001)." (PMID 29929486, 2018). "The magnitude of the postoperative SIR, evidenced by CRP, was significantly associated with long-term outcomes following surgery for colorectal cancer, independent of complications and stage." (PMID 27016295, 2016). "Some studies have concluded that elevated CRP levels are not an independent negative predictor of survival, whereas others have reported that CRP has a prognostic significance in colorectal cancer, suggesting the presence of a detrimental systemic inflammatory response." (PMID 26848624, 2016). "Although pre-diagnostic concentrations of these biomarkers, especially C-reactive protein, have been associated with a higher risk of colorectal cancer in some studies, this association does not seem to have a robust support without hints of bias." (PMID 26321888, 2015). "Whether the inflammatory reaction, which is reflected by increased CRP serum levels, can be treated with anti-inflammatory drugs in order to improve prognosis—as investigated in other solid tumors, such as colorectal cancer—is unclear to date." (PMID 26248232, 2015). "In colorectal cancer, high CRP strongly predicted survival in 36 (75%) studies." (PMID 26717416, 2015). "Given the aberrantly activated Wnt signaling and highly induced CRP expression in tumors, topical targeting both molecules may be a potential option for colorectal cancer therapy." (PMID 25025473, 2014). "We retrospectively evaluated whether CRP adds to prognosis information in stage I–III colorectal cancer patients with poor lymph node assessment." (PMID 23833661, 2013). "Preoperative serum VEGF and CRP level increased in colorectal cancer patients." (PMID 20465852, 2010). "Several studies have reported that in occurrence, progression, metastasis, and recurrence of colorectal cancer, systemic inflammation has an important role, and that CRP may be a useful indicator of inflammatory response." (PMID 20465852, 2010). "Therefore, the objective of the current investigation is to assess the prognostic significance of preoperative serum VEGF, IL-6, and CRP levels as indicators of outcome in patients with colorectal cancer." (PMID 20465852, 2010). "High serum CRP concentrations have been correlated with elevated IL-6 serum concentrations and with poor prognosis in solid tumours such as colorectal cancer and with mortality in RCC." (PMID 20808314, 2010). "The present study evaluated the relationship between C-reactive protein concentrations and survival in a cohort of patients receiving adjuvant 5-fluorouracil (5-FU) chemotherapy following potentially curative resection for colorectal cancer." (PMID 16721360, 2006). "Indeed, the combination of pathological stage and C-reactive protein has recently been used to improve the prediction of outcome in patients who underwent potentially curative resection for colorectal cancer." (PMID 16685271, 2006). "It has been previously shown that, in patients with primary operable colorectal cancer, approximately one-third of patients had an elevated circulating concentration of C-reactive protein preoperatively and that these patients had a significantly poorer outcome." (PMID 15597096, 2005).